HSPB8 (heat shock protein family B (small) member 8)
Diseases named in the same sentence as HSPB8 in open-access papers (continued):
Sharing a sentence is not in itself a finding about the gene and the disease.
myopathy (24 papers, 2017 to 2025). A disease of the muscle in which the muscle fibers do not function properly. "In contrast, frameshift HSPB8 mutations cause a unique myopathy with myofibrillar aggregates and rimmed vacuoles, with or without distal motor neuropathy." (PMID 40467930, 2025). "Frameshift mutations in the C-terminal domain (CTD), resulting in elongation of the HSPB8 C-terminal, cause myopathy with myofibrillar pathology and rimmed vacuoles." (PMID 40243504, 2025). "Instead, myopathies are the predominant pathological conditions of a group of HSPB8 frameshift mutations." (PMID 36594740, 2023). "Since HSPB8 frameshift mutations have only been reported in (neuro)myopathy patients, it is likely that they primarily affect muscle tissue." (PMID 36854646, 2023). "Like BAG3, HSPB8 mutations have been described in distal hereditary motor neuropathy, axonal Charcot-Marie-Tooth disease, and myopathies." (PMID 36594740, 2023). "HSPB8 K141 mutations have been mainly described in motor neuropathies (as HSPB8 P90L and N138T), with few reports that associated this substitution (HSPB8 K141E) with rimmed vacuolar myofibrillar myopathy." (PMID 36854646, 2023). "For example, mutations in DNAJB6 (homolog of dnj-24) lead to Limb-girdle muscular dystrophy 1E, and mutations in HSPB8 (homolog of hsp-12.2) or BAG2 (homolog of unc-23) were associated with myopathies." (PMID 35733850, 2022). "We found evidence for 31/50 chaperones, including 17 chaperones that were associated with muscle diseases (e.g., HSPB8 with myopathies) and 27 chaperones that were associated with muscle function (e.g., the myosin chaperone UNC45B)." (PMID 33846299, 2021). "This suggests that some loss-of-function mechanisms also play a role in the development of HSPB8-associated myopathy." (PMID 28780615, 2018). "Regarding the HSPB8 frameshift mutations, initial studies had suggested the possibility that the myopathy may be caused by HSPB8 haploinsufficiency by induction of nonsense-mediated mRNA decay or protein degradation." (PMID 40243504, 2025). "Interestingly, the K141N and K141E missense mutations in HSPB8 associated with dHMN and myopathy reduce the ability of HSPB8 to bind to BAG3, and impair the degradation of aggregates via autophagy in vitro and in vivo." (PMID 28780615, 2018). "Apart from rare exceptions, missense mutations tend to be associated with dHMN or CMT2L while frameshift mutations in the C-terminal domain of HSPB8, leading to C-terminal elongation, result in myopathy with myofibrillar pathology and rimmed vacuoles." (PMID 40243504, 2025). "HSPB8 myopathy was first described in 2016 in two families presenting with a distal neuromyopathy phenotype." (PMID 40243504, 2025). "Since the initial submission of this review, HSPB8-myopathy has been referenced in the Online Mendelian Inheritance in Man (OMIM) as myofibrillar myopathy type 13 (MFM13) with rimmed vacuoles." (PMID 40243504, 2025). "Fibroblasts from a patient with HSPB8-myopathy showed reduced expression of HSPB8 and increased expression of both the autophagosomal marker LC3B and autophagy receptor p62, compared to control fibroblasts." (PMID 40243504, 2025). "On muscle biopsy, typical myofibrillar myopathy changes are seen, including rimmed vacuoles and aggregates reactive for myotilin, αB-crystallin, dystrophin, HSPB8, DNAJB6, myotilin, BAG3, TDP43 and ubiquitin." (PMID 39501809, 2024). "HSPB8 mutations are causative of dHMNs, CMT2 and myopathies, characterized by high variability in onset and progression." (PMID 35281256, 2022).
myopathy (continued). "Among these proteins, some are associated with a primarily neuromuscular disorder (TELT, HSPB8, HXK1, PRPS1) or myopathy (LDHA)." (PMID 34360601, 2021). "The reported pathological features in all HSPB8-related myopathies have been similar: dystrophic changes and MFM pathology with protein aggregates (desmin, myotilin, CRYAB, dystrophin, HSPB8, DNAJB6, myotilin, BAG3, TDP-43, and ubiquitin) and rimmed vacuoles." (PMID 32093037, 2020). "Given the role of HSPB8 in the CASA pathway, which is reported to be essential for muscle maintenance, HSPB8-related myopathy has been proposed to be due to impaired CASA function." (PMID 32093037, 2020). "Our data, therefore, suggest that toxic gain-of-function of mutant Hspb8 aggregates is a major contributor to the peripheral neuropathy and the myopathy." (PMID 28780615, 2018). "Since then, only a few additional patients with HSPB8-myopathy have been reported." (PMID 40243504, 2025). "Only the HSPB8 p.P173Sfs*43 was also reported in myopathy with neurological involvement." (PMID 36854646, 2023). "For instance, cells expressing HSPB8 K141N mutant showed impaired Nrf2 nuclear translocation which was reverted by antioxidants, and similar alterations have been observed in cells expressing the myopathy-related BAG3 P209L mutant." (PMID 35281256, 2022). "Notably, HSPB8-myopathy appears to be due to a gain-of-function mutant Hspb8 rather than its lack, as muscle function in homozygous knockout mice is marginally affected compared to knockin animals overexpressing a pathogenic version." (PMID 34740639, 2022). "Hspb8 knockout mice do not develop a neuropathy, myopathy or myofibrillar pathology, suggesting that the p.K141N mutation exerts a dominant toxic effect." (PMID 39501809, 2024). "In addition, resemblance to other myofibrillar myopathies was observed as myotilin-positive myofibrillar lesions also contain BAG3 and HSPB8." (PMID 33974137, 2021). "Considering this HSPB8 role, it is not surprising to also see small TIA1 positive inclusions in HSPB8 myopathy." (PMID 40243504, 2025).
tumor (23 papers, 2012 to 2026). "Restored expression of H11/HspB8 causes growth arrest and inhibits tumor growth through the activation of programmed cell death pathways." (PMID 23056924, 2012). "Regarding tumor T and N stages, HSPB8 expression was significantly higher in T2 groups than in T3 group, and lower in N1 groups than in N0 groups." (PMID 41190325, 2025). "We compared expression differences of HSPB8 among different patient groups and clinical phenotypes we focused on included age, tumor T and N stage, Gleason score and PSA." (PMID 41190325, 2025). "During tumor development, HSPB8 plays an opposite role—pro-tumoral or anti-tumoral—depending on the tumor type." (PMID 41190325, 2025). "For tumor N stage, patients in N1 stage exhibited lower HSPB8 expression levels compared to those in N0 stage (p < 0.001)." (PMID 41190325, 2025). "We found a positive correlation between tumor progression indicators, such as staging, and HSPB8 expression levels, both in our tissue samples and in international public databases." (PMID 38213722, 2024). "The results indicated not only that the overexpression of HSPB8 was pronounced in BCa tissues but also that HSPB8 expression was positively correlated with tumor stage." (PMID 38213722, 2024). "Seven hub genes (AXL, EFEMP2, VIM, EHD2, FSTL3, ALOX5, HSPB8) were downregulated in tumor samples, while COL3A1 was upregulated in tumor samples in the TCGA dataset." (PMID 37291533, 2023). "Loss of MUC2, HSPB8, and SCG2 completely disrupted the formation of tumor spheroids in cells expressing ZEB1." (PMID 35440541, 2022). "These aspects must be taken into account when therapeutic approaches aimed to up- or downregulate HSPB8 expression are tested and their use should be carefully tailored for each specific form and stage of tumor." (PMID 33562660, 2021). "Its restored expression induces cell death and inhibits tumor growth in xenograft models, identifying H11/HspB8 as a tumor suppressor." (PMID 23056924, 2012). "Significantly, H11/HspB8 is also silenced in a high proportion of atypical nevi, but not in most benign nevi, suggesting that its silencing contributes to tumor progression." (PMID 23056924, 2012). "Significantly, the ΔPK oncolytic activity also includes the activation of multiple programmed cell death (PCD) pathways and is accompanied by the upregulation of H11/HspB8 that functions as a tumor suppressor." (PMID 23056924, 2012). "Importantly, our study's primary objective was to explore the function exerted by HSPB8 in tumor cells." (PMID 38213722, 2024). "In conclusion, these results indicated that HSPB8 played a remarkable role as a tumor promotor and might be regarded as a promising therapeutic target for more effective treatment of BCa." (PMID 38213722, 2024). "Therefore, we inferred that HSPB8 impacts the immune microenvironment of BC participates in the regulation of BC tumor immunity can be used as a prognostic indicator for BC and can reflect the immune status of patients." (PMID 35330734, 2022). "Indeed, recently prognostic prediction model based on autophagy-related gene (ARG) signature studies conducted in a variety of tumors to correlate clinical stage and survival with autophagy genes indicated HSPB8 as a prognostic ARG for tumor progression." (PMID 36400750, 2022). "SERPINA1, MAP1LC3A, DIRAS3 were down-regulated in a high risk group and up-regulated in a low risk group, which were potentially tumor suppressor genes; HSPA8, HSPB8 were up-regulated in a high risk group and down-regulated in a low risk group, which were probably promoting oncogenes." (PMID 34876005, 2021). "On the protein level, we validated these hub genes expressions of normal tissues and tumor tissues through the HPA database.HSPA8 and HSPB8 expressed higher in tumor tissues than that in normal tissues, while SERPINA1 and DIRAS3 expressed higher in normal tissues against tumor tissues." (PMID 34876005, 2021).
tumor (continued). "HSPB8 expression and role are tumor-specific, showing a dual and opposite role." (PMID 33562660, 2021). "Accordingly, HSPB8 was identified as a candidate tumor progression gene." (PMID 31614463, 2019). "Surprisingly, in other tumor types HSPB8 expression correlates with increased aggressiveness." (PMID 28060751, 2017). "Indeed, caspase-1 cleaved the haploinsufficient tumor suppressor Beclin-1 that was also upregulated by H11/HspB8 through a TAK1/mTORC1 pathway that involved mTOR phosphorylation at S2481, which is the site of intrinsic mTORC1-specific catalytic activity." (PMID 23056924, 2012). "Also characteristic of tumor suppressors is the cell-type specificity of the H11/HspB8 effects and the finding that it can undergo single-site transforming mutation." (PMID 23056924, 2012). "This study revealed the growth-inhibitory effects of hyperthermia treatment against TNBC cells and indicated that hyperthermia can induce M1 polarization of macrophages via exosome-mediated HSPB8 transfer, which may remodel the tumor immune microenvironment of TNBC." (PMID 37233869, 2023). "Quantitative analysis of tumor-infiltrating immune cells (TIICs) and functional assays revealed significant differences in the roles of ACE and HSPB8 between normal lung and LUSC cells, underscoring their importance in tumor biology and epigenetic regulation." (PMID 41490177, 2026). "The effects of HSPB8 and BAG3 on lung metastasis of tumors in vivo were verified by constructing a metastatic tumor model." (PMID 39215616, 2024). "We observed a decreasing expression level of HSPB8 and PRKN and an increasing expression level of EGFR, CDKN2A, FADD, and ITGA3 in tumor samples." (PMID 33456497, 2020). "Both ACE and HSPB8 showed significant negative correlations with mRNAsi, indicating involvement in tumor cell differentiation, growth rate, and invasiveness modulation, underscoring their potential as therapeutic targets in LUSC." (PMID 41490177, 2026). "The experiments showed that HSPB8 and BAG3 were highly expressed in ICC and may play a significant role in tumor progression." (PMID 39215616, 2024). "In fact, HSPB8 is both expressed in human HCC tumors and the adjacent non-tumor liver tissues." (PMID 33562660, 2021). "In fact, HSPB8 silencing in tamR MCF-7 cells reduces their proliferation and, surprisingly enough, this effect is enhanced in the presence of tamoxifen, which is not expected to exert any role in the tumor properties of these cells." (PMID 33562660, 2021). "While H11/HspB8 has two heat-shock-factor- (HSF-) binding sites, 1,000 bases upstream of the translation initiation site, its expression is not always heat inducible and it appears to differ in tumor as compared to normal cells." (PMID 23056924, 2012).
neurodegenerative disease (12 papers, 2013 to 2025). A disorder of the central nervous system characterized by gradual and progressive loss of neural tissue and neurologic function. "Growing evidence points towards a role of HSPB8 in chaperone-associated autophagy, which has been shown to be a determinant for the clearance of poly-glutamine aggregates in neurodegenerative diseases but also for the maintenance of skeletal muscle myofibrils." (PMID 28780615, 2018). "It must also be noted that the prodegradative and/or antiaggregation activity of HspB8 is also detectable using other protein prone to misfold and linked to different neurodegenerative diseases." (PMID 23810450, 2013). "In summary, our data provide clear evidence that upregulation of HSPB8 could be an effective approach to combating those neurodegenerative diseases that are characterized by (motor) neurone loss and proteinaceous inclusions." (PMID 27466192, 2016). "By analyzing the activation of the HspB8 promoter we found that it is positively regulated by proteasome inhibition (data confirmed also by WB analysis), a condition paralleled by a compensatory autophagy activation and triggered by misfolded proteins causative of neurodegenerative diseases." (PMID 23810450, 2013). "HSPB1 and HSPB5 are upregulated in neurodegenerative diseases, especially in reactive glial cells and HSPB8, together with BAG3, is upregulated in astrocytes." (PMID 33330614, 2020). "The pro-degradative activity of HSPB8 is not limited to TDP-43, but it is exerted also on a number of other mutated proteins linked to neurodegenerative diseases." (PMID 28608264, 2018). "HSPB8 is a core component of the Chaperone-Assisted Selective Autophagy (CASA) complex and counteracts misfolded protein accumulation in neurodegenerative diseases." (PMID 40725218, 2025). "Out of 10 mammalian sHSPs, four family members are expressed in neurons and play a role in neurodegenerative diseases: HSPB1, HSPB5, HSPB8 and to a lower extend, HSPB6." (PMID 33330614, 2020). "Altogether, the study here reported has shown that HSPB8 recognizes and facilitates clearance of insoluble species of these peculiar DPRs, whose structures may not reflect those typically formed by “classical” misfolded proteins responsible for neurodegenerative diseases." (PMID 28608264, 2018).
neuromuscular disease (12 papers, 2017 to 2025). "The novel HSPB8_fs mutations associated with neuromuscular diseases are predicted to encode for elongated HSPB8 proteins." (PMID 36854646, 2023). "Here, we employoptical tweezers to explore the mechanisms of action of the humansmall heat shock protein HSPB8 and its pathogenic mutant K141E, whichis associated with neuromuscular disease." (PMID 37411010, 2023). "To conclude, the HSPB8_fs mutations related to neuromuscular diseases alter HSPB8 solubility, causing its accumulation into cytoplasmic aggregates and relocation of the CASA complex factors." (PMID 36854646, 2023). "Different neuromuscular disease-associated frameshift (fs) mutations in the HSPB8 gene result in encoded HSPB8 proteins with a common aberrant C-terminal extension." (PMID 37462824, 2023). "To date, mutations in the genes coding for HspB1, HspB3, HspB5, and HspB8 have been associated with neuromuscular diseases." (PMID 34487489, 2021). "Of interest, mutations in other HSPBs, in addition of HSPB8, cause neuromuscular diseases." (PMID 40243504, 2025). "Four of these sHSP genes carry known mutations which have been associated with neuromuscular disease phenotypes in humans: HspB1 (Hsp27, Hsp25), HspB3, HspB5 (αB-crystallin), and HspB8 (Hsp22), not counting polymorphisms or other sequence variants with unclear relation to disease." (PMID 35678958, 2022). "In this review, we cover mutations in DNAJB6, DNAJB2, αB-crystallin (CRYAB, HSPB5), HSPB1, HSPB3, HSPB8, and BAG3, and discuss the molecular mechanisms by which they cause neuromuscular disease." (PMID 32093037, 2020). "Of the 10 sHSPs (or HSPBs) encoded by the human genome, four are currently known to be associated with neuromuscular disease; these are HSPB1 (Hsp27), HSPB3, αB-crystallin (CRYAB, HSPB5), and HSPB8 (Hsp22)." (PMID 32093037, 2020).
peripheral neuropathy (7 papers, 2018 to 2025). A disorder affecting the peripheral nervous system. "We found three mutations of the K141 residue (K141N, K141E, and K141T) in HSPB8 from a patient cohort with inherited peripheral neuropathy." (PMID 36979812, 2023). "HspB1 harbored by far most of the mutations as compared to HspB3 and HspB8: In a systematic study of a cohort of 510 unrelated index patients with peripheral neuropathies, 32 patients were found to have mutations in sHSPs (32/510; 6.3%)." (PMID 35678958, 2022). "In this paper, we will first summarize how mutations in HSPB1, HSPB3, and HSPB8 cause hereditary peripheral neuropathies." (PMID 32323160, 2020). "Mutations in HSPB8 associated with peripheral neuropathy (K141E and K141N) significantly reduce its efficiency in preventing ataxin-3 and P182L-HSPB1 aggregation, indicating that loss of HSPB8 function may accelerate the progression of these protein misfolding-associated diseases." (PMID 40385290, 2025). "Additionally, it is relevant that peripheral neuropathy can be caused by pathogenic variants in mitochondrial protein chaperones such as HSPB8 (HSP22), HSPB1(HSP27), and TID1, and that modulating chaperones can improve sensory fiber recovery in diabetic peripheral neuropathy." (PMID 33810506, 2021). "HSPB mutations may have serious consequences, such as peripheral neuropathy caused by point mutations in HSPB1 and HSPB8." (PMID 36213445, 2022).
cardiac diseases (5 papers, 2009 to 2024). "In rodent heart disease models, HSPB8 was shown to translocate to the mitochondrial inner membrane where it stimulated mitochondrial oxidative phosphorylation." (PMID 36979812, 2023).
infection (5 papers, 2015 to 2024). The state of being infected such as from the introduction of a foreign agent such as serum, vaccine, antigenic substance or organism. "This implied that lentivirus achieved widespread infection within brain tissues with high efficiency and allowed a widespread and persistent HSPB8 overexpression." (PMID 32889520, 2020).
neurological disease (3 papers, 2014 to 2025). "The spectrum of neurological disorders associated with HSPB8 is in continuous expansion and can involve motor axons, peripheral nerves, and muscles, in isolation or in combination." (PMID 40243504, 2025). "HSPB8 gene alteration and mutations have been reported in neurological disease." (PMID 25051369, 2014).
inflammation (2 papers, 2020 to 2021). Aberrant reaction of the microcirculation characterized by movement of fluid and leukocytes from the blood into extravascular tissues. "At the same time, HSPB8 was found to be highly expressed in synovial tissues from RA patients, and the release of HSPB8 in the synovial joint could potentially lead to an ongoing activation of inflammatory cells, thereby amplifying the inflammatory loop of synovial inflammation." (PMID 33562660, 2021).